FHL1 (four and a half LIM domains 1)
Diseases named in the same sentence as FHL1 in open-access papers (continued):
Sharing a sentence is not in itself a finding about the gene and the disease.
cancer (continued). "FHL1 knockdown cancer cells or FHL1 KO MEFs displayed shorter survival upon exposure to IR." (PMID 32587768, 2020). "Interestingly, cancer cells frequently overexpress factor H, and factor H-like protein 1 (FHL-1), soluble proteins that are already present at high concentrations in plasma." (PMID 33167384, 2020). "In this review, we focus on the function of FHL1 (FHL1A) in cancer." (PMID 32587768, 2020). "In addition to the significant research progress regarding the function of FHL1 in skeletal muscle myopathies and cardiovascular diseases, studies on the involvement of FHL1 in cancer have grown exponentially." (PMID 32587768, 2020). "FHL1 knockdown cancer cells or FHL1 KO MEFs exhibited decreased survival on exposure to IR." (PMID 28094252, 2017). "FHL1 knockdown in cancer cells or FHL1 KO in MEFs abrogated IR-induced G2/M arrest." (PMID 28094252, 2017). "Although the role of FHL1 in cancer development and progression is well established, the detailed mechanisms of how FHL1 is down-regulated during carcinogenesis remain unknown." (PMID 25272045, 2014). "Furthermore, using DNA bisulfite modification and sequencing experiments, we demonstrated that the FHL1 promoter is hypermethylated in cancer cells." (PMID 25272045, 2014). "Interestingly, several studies have reported marked downregulation of FHL1 in various cancer types, including lung, prostate, breast, ovarian, colon, thyroid, brain, renal, oral, liver, and gastric cancer, supported by microarray profiling and immunohistochemical analysis of human patient tissues." (PMID 32587768, 2020). "FHL1 acts in activation of the tumor suppressor gene p21 and repression of the oncogene c-myc through physically and functionally interacting with Smad2, Smad3 and Smad4 that are important regulators of cancer development and progression in a casein kinase 1δ-dependent manner." (PMID 30379883, 2018). "In addition, FHL1 knockdown cancer cells or FHL1 KO MEFs had enhanced CDC2 activity." (PMID 28094252, 2017). "By contrast, CDKN1A and CDKN2A encode p21Cip1 and p16Ink4a, respectively, which are potent cell-cycle inhibitors in MCL, whereas FHL1 has been revealed to induce G1 and G2/M cell-cycle arrest by activating CDKN1A in human cancers." (PMID 36675119, 2023). "Thus, some researchers considered that FHL1 may have promoting effects in cancer." (PMID 35142956, 2023). "We also verified the binding of FHL1 with CDC25A and CHK1 proteins, which reportedly interact with FHL1 in other cancer cells." (PMID 35142956, 2023). "Expression of several genes known to be involved in cancer progression were identified by this method, including HMGA2, FHL1, SLC2A3, ADAMTS1, UPP1, and TGM2." (PMID 32054828, 2020). "We found that IR-inducible LIM proteins, such as FHL1, inhibit CDC25C activity, resulting in radioresistance in cancer cells." (PMID 28094252, 2017). "FHL1 expression, induced by ionizing irradiation in a SP1- and MLL1-dependent manner, positively correlates with radioresistance in cancer patients." (PMID 28094252, 2017). "Moreover, targeted bisulfite NGS methodology validated microarray data on four selected genes (GNL3L, FHL1, FLNA, and PGRMC1), confirming that they were hypomethylated in patients with cancer anorexia in comparison with controls." (PMID 39519555, 2024). "Furthermore, we found that FHL1 interacts with CDC25C, which was confirmed as an important factor in cancer development." (PMID 35142956, 2023). "Although liver-derived factor H and FHL-1 is almost certainly present in the TME, production of these proteins by cancer cell may ensure that local concentrations are sufficient to protect the cells." (PMID 33167384, 2020). "DNA hypermethylation of FHL1 have been detected in certain cancer types, no further findings have been reported yet in HNSCCs." (PMID 26908444, 2016).
cancer (continued). "Here, we show that LIM domain-containing proteins, such as FHL1, increase inhibitory CDC25 phosphorylation by forming a complex with CHK2 and CDC25, and sequester CDC25 in the cytoplasm by forming another complex with 14-3-3 and CDC25, resulting in increased radioresistance in cancer cells." (PMID 28094252, 2017).
cardiac disease (7 papers, 2020 to 2026). "Molecular detection can be determined in EMD and FHL1 pathogenic variants for asymptomatic patients because heterozygous women are at risk of developing heart disorders and muscular dystrophy syndromes." (PMID 34356086, 2021). "FHL1 encodes a protein essential for sarcomere function and cardiac and skeletal muscle biomechanics, with pathogenic variants linked to neuromuscular and cardiac diseases, including HCM and arrhythmias." (PMID 41287789, 2025). "Patients with mutations in FHL1 are not expected to have a higher risk of thromboembolic events than expected from the underlying risk of cardiac disease and the autopsy report did not suggest that EDMD6 was the cause of death." (PMID 35607917, 2022). "The consensus SDGs include novel as well as known genes in mouse heart development or cardiac diseases, such as PICALM interacting mitotic regulator (Fam64a), four and a half LIM domain protein 1 (Fhl1), and others." (PMID 37322439, 2023). "Similarly, induction of the FHL-1 expression in the LV tissue has been observed in animal models of left heart hypertrophy induced by TAC, as well as in patients with left heart diseases." (PMID 31980934, 2020).
cardiovascular diseases (3 papers, 2020 to 2025). "From the 42 DASGs-DEGs-overlap genes, we selected Fn1, Fhl1 and Postn for qRT-PCR validation based on the gene expression levels in samples, FC value and correlation with cardiovascular diseases." (PMID 36435743, 2022).
infection (3 papers, 2021 to 2025). The state of being infected such as from the introduction of a foreign agent such as serum, vaccine, antigenic substance or organism. "With this present study showing upregulation of FHL1, both of our studies suggest a novel strategy by which alphaviruses are likely to facilitate infection by upregulating certain host factors which are critical for virus replication." (PMID 37884534, 2023). "From the observations above, we hypothesized that FHL1 might also play a significant role in infection and disease of other clinically important arthritogenic alphaviruses such as RRV, MAYV and ONNV." (PMID 37884534, 2023). "It is therefore tempting to speculate that the ongoing high levels of FHL1 in chronic CHIKV infection may facilitate the persistence of infection which leads to chronic disease development." (PMID 37884534, 2023). "Host factors, including TIM-1, FHL1, and TSPAN9, are known to facilitate CHIKV entry and promote infection, whereas others, such as IFITM3, inhibit viral adsorption by limiting membrane fusion and virion internalization." (PMID 39917312, 2025). "Indeed, it has recently been shown that the four-and-a-half LIM domain protein 1 (FHL1) is a host factor required for the infection of fibroblasts and skeletal muscles cells by CHIKV but that the absence of the latter did not prevent the entry of MAYV into these cells." (PMID 33799906, 2021). "Consistent with this, our analysis confirmed that only nsP3 of CHIKV and ONNV were able to interact with FHL1 supporting our hypothesis that FHL1:nsP3 interaction is the key factor in the dependency of CHIKV and ONNV, but not RRV or MAYV on FHL1 for optimal infection." (PMID 37884534, 2023).
muscular disorders (2 papers, 2013 to 2023). "Importantly, cyclin A1 RNA levels of FSHD were not only higher compared to healthy controls but also to patients with the other muscular disorders: CAV3, DYSF, and FHL1." (PMID 24019929, 2013).
digestive system cancer (1 paper, 2014). A primary or metastatic malignant neoplasm involving any part of the digestive system. "Our results suggest that miR-410 may function as an oncomiR and are consistent with its key function in regulating FHL1 in certain digestive system cancers." (PMID 25272045, 2014).
FHL1 also shares sentences with these, for which no sentence is quoted: reducing body myopathy (6 papers); skeletal muscle disorder (4); glioblastoma (3); heart failure (3); viral infections (3); atrial fibrillation (2); endometrial carcinoma (2); esophageal squamous cell carcinoma (2); myotonic dystrophy (2); neuromuscular disease (2); osteosarcoma (2); renal carcinoma (2); scapuloperoneal myopathy (2); acute myeloid leukemia (1); alcoholism (1); amyloid (1); amyotrophic lateral sclerosis (1); astrocytoma (1); Ataxia (1); autism (1); brain tumors (1); breast adenocarcinoma (1); carotid atherosclerosis (1); centronuclear myopathy (1); chronic asthma (1); epilepsy (1); Friedreich ataxia (1); germ cell tumor (1); hemochromatosis (1); hereditary cardiomyopathies (1).
A further 24 diseases each share a sentence with FHL1 in 1 paper.